LINP1 (lncRNA in non-homologous end joining pathway 1)
Synonyms: PARROT; LINC00707
Gene: Long non-coding RNA gene on chromosome 10 (6,682,513 to 6,879,450, forward strand). Ensembl gene ENSG00000223784.
Diseases named in the same sentence as LINP1 in open-access papers:
LINP1 is named in the same sentence as 33 diseases in open-access papers, as found by Europe PMC text mining. Sharing a sentence is not in itself a finding about the gene and the disease. The quoted sentences say what the papers report.
breast cancer (20 papers, 2016 to 2026). A primary or metastatic malignant neoplasm involving the breast. "Clinical data show that elevated LINP1 levels in tumors are associated with poorer overall survival and disease-free survival in breast cancer patients." (PMID 39479021, 2024). "The overexpression of the lncRNA LINP1 is positively associated with proliferation, drug resistance, and metastasis in breast cancer cells." (PMID 37242146, 2023). "LINP1 upregulation has a positive association with drug-resistance and unfavorable prognosis, and is seen in breast cancer cells resistant to 5-FU and doxorubicin." (PMID 34425750, 2021). "Since the original study, the role of LINP1 in breast cancer metastasis and its association with Ku and DNA-PKcs has been supported by other reports." (PMID 33045735, 2020). "Upregulated LINP1 expression in cancer of the breast was also linked to a poor prognosis." (PMID 41459628, 2026). "Knockdown of LINP1 leads to reduced breast cancer cell growth by inducing G1-phase cell cycle arrest and promoting apoptosis." (PMID 39479021, 2024). "The top ranked lncRNA in lncRNA-Topic 8 is LINP1, a regulator of DNA repair in triple-negative breast cancer, whose knockdown increases the sensitivity of breast cancer cells to radiotherapy." (PMID 38611028, 2024). "Inhibition of LINP1 expression in breast cancer cell lines promotes apoptosis and induces cell cycle arrest." (PMID 32913451, 2020). "The expression of LINP1 was shown to be upregulated in tamoxifen-resistant breast cancer cells, and its subsequent knockdown using targeted siRNAs resulted in increased tamoxifen-induced apoptosis, and thus less resistance to tamoxifen treatment." (PMID 32466143, 2020). "To determine if LINP1 and PAXX compete for Ku in cells, we determined LINP1 localization in MDA-231 breast cancer cells using single-molecule RNA fluorescence in situ hybridization (FISH)." (PMID 33045735, 2020). "In vitro and in vivo investigations showed that LINP1 silencing decreased resistance to this drug and the viability of resistant breast cancer cells." (PMID 32759784, 2020). "LINP1 knock-down promoted doxorubicin-induced apoptosis in TNBC cell lines, while overexpression of LINP1 in an estrogen-receptor positive breast cancer cell line with untraceable LINP1 inhibited the apoptotic effects of doxorubicin in these cells." (PMID 28868264, 2017). "The study clearly identified TNBCs as exhibiting elevated levels of LINP1 expression when compared with other breast cancer subtypes." (PMID 27551547, 2016). "LINP1 is involved in breast cancer cell proliferation, metastasis, and chemoresistance." (PMID 39479021, 2024). "Additionally, LINP1 facilitates breast cancer cell metastasis and modulates the expression of markers related to epithelial-mesenchymal transition (EMT)." (PMID 39479021, 2024). "LINP1 can also inhibit breast cancer cell apoptosis induced by chemotherapeutic drugs." (PMID 35402492, 2022). "The 5-FU and DOX resistance of breast cancer cells are increased by LINP1." (PMID 34425750, 2021). "LINP1 also promotes the proliferation of ER-positive MCF7 breast cancer cells." (PMID 32486413, 2020). "Accordingly, LINP1 modulated IR sensitivity in breast cancer cells." (PMID 27551547, 2016). "LINP1 levels were correlated with EGFR expression in primary breast cancers and CCLE cell lines." (PMID 27551547, 2016). "Notably, inhibition of LINP1 enhances the sensitivity of breast cancer cells to radiotherapy." (PMID 39479021, 2024). "Thus, LINP1 has an important role in tamoxifen resistance and could be a putative target to enhance the efficiency of tamoxifen therapy in breast cancer." (PMID 32759784, 2020).
breast cancer (continued). "LINP1, which promotes the proliferation of ER-positive MCF7 breast cancer cells, is negatively regulated by estrogen and upregulated in MCF7 and T47D and tamoxifen-resistant breast cancer cells derived from these cells." (PMID 36358625, 2022). "The lincRNA termed lncRNA in non-homologous end joining (NHEJ) pathway 1 (LINP1), which was first determined to be overexpressed in triple-negative breast cancer, improves tamoxifen resistance in ER+ breast cancer." (PMID 36358625, 2022). "LINP1 is expressed at higher levels in breast cancer patients with distant metastasis than in those without distant metastasis." (PMID 32913451, 2020). "The lncRNA in non-homologous end joining pathway 1 (LINP1) is overexpressed in tamoxifen-resistant breast cancer cells." (PMID 32759784, 2020). "LINP1 was identified as overexpressed in triple-negative breast cancers (TNBCs) when compared with other breast cancer subtypes using RNA-seq data from The Cancer Genome Atlas and the Cancer Cell Line Encyclopedia (CCLE)." (PMID 27551547, 2016). "LINP1 knockdown enhanced apoptosis in TNBC cell lines following doxorubicin treatment, a chemotherapy drug for TNBC, while overexpression of LINP1 in an estrogen-receptor positive breast cancer (ER+ BC) cell line with undetectable LINP1 protected these cells from doxorubicin-induced apoptosis." (PMID 27551547, 2016). "In addition, LINP1 expression is negatively regulated by estrogen, and is upregulated in ER-positive breast cancer cell lines, MCF7 and T47D, under estrogen-deprived or tamoxifen-treated conditions, as well as in tamoxifen-resistant breast cancer cells derived from these cell lines." (PMID 32486413, 2020).
cervical cancer (8 papers, 2020 to 2025). A primary or metastatic malignant neoplasm involving the cervix. "In cervical cancer, LINP1 translocates from the cytoplasm to the nucleus to bind Ku80 and DNA-PKcs to promote DNA damage repair during radiotherapy." (PMID 36918934, 2023). "LINP1 levels are also upregulated in cervical cancer, prostate cancer and lung cancer, suggesting that the LINP1 RNA-dependent repair mechanism, which facilitates NHEJ in tumors, is utilized broadly in multiple cancer sub-types." (PMID 33045735, 2020). "LINP1 was shown to be highly expressed in cervical cancer tissues and HeLaS3 cells." (PMID 35692795, 2022). "It is thought that the expression of LINP1 may be regulated by the EGFR pathway in cervical cancer cells." (PMID 35692795, 2022). "Therefore, LINP1 may serve as a prognostic marker and a potential therapeutic target for cervical cancer treatment." (PMID 35692795, 2022). "LncRNAs MEG3, CRNDE, LINP1 and SNHG20 are shown to influence cervical cancer progression and we report G4 specific protein partners for these lncRNAs." (PMID 37628839, 2023).
triple-negative breast carcinoma (6 papers, 2018 to 2025). An invasive breast carcinoma which is negative for expression of estrogen receptor (ER), progesterone receptor (PR), and human epidermal growth factor receptor 2 (HER2). "LINP1 was initially identified in triple-negative breast cancer (TNBC) to be functional in non-homologous end joining (NHEJ) by serving as a scaffold to connect Ku80 and DNA-PKCs for enhancing double-strand DNA break repair." (PMID 36918934, 2023).
prostate carcinoma (5 papers, 2020 to 2024). A carcinoma that arises from epithelial cells of the prostate gland. "The expression level of LINP1 is notably up-regulation in prostate cancer tumor tissues than in adjacent tumor tissues, and the OS time of high LINP1expression patients is notably shorter than these with low LINP1 expression." (PMID 32913451, 2020). "LINP1 expression is also related to T stage, lymph node metastasis, and distant metastasis in prostate cancer." (PMID 32913451, 2020).
acute myeloid leukemia (2 papers, 2021 to 2023). Acute myeloid leukemia (AML) is a group of neoplasms arising from precursor cells committed to the myeloid cell-line differentiation. "In pediatric and adolescent acute myeloid leukemia (AML) lncRNA, LINP1 was found to be overexpressed at diagnosis and reduced after complete remission." (PMID 34771521, 2021).
colon carcinoma (2 papers, 2016 to 2023). "Transduction of miR-29 mimic into TBNC and isogenic colon cancer cells resulted in LINP1 downregulation irrespective of genotype, and repressed luciferase reporter expression for wild-type LINP1, but not a LINP1 with a miR-29 seed-sequence mutation." (PMID 27551547, 2016).
Pancreatic cancer (2 papers, 2022 to 2024). "Under the LASSO regression and multivariate Cox regression analysis, five lncRNAs(ZNF236-DT, CASC8, PAN3-AS1, SH3PXD2A-AS1, LINP1) of them were selected to establish the novel prognostic FRLS for predicting the OS of patients with pancreatic cancer." (PMID 35330729, 2022). "Consistent with the findings of A-Y Chen, we found that the proliferation, invasion, and migration ability of Pancreatic cancer cells decreased remarkably in LINP1 knockdown group, compared to the si-NC group." (PMID 35330729, 2022). "In summary, we identified the prognostic ferroptosis-related lncRNAs(ZNF236-DT, CASC8, PAN3-AS1, SH3PXD2A-AS1, LINP1) in pancreatic cancer and these lncRNAs may serve as therapeutic targets for pancreatic cancer." (PMID 35330729, 2022). "The present study implicates that several ferroptosis-related lncRNAs(ZNF236-DT, CASC8, PAN3-AS1, SH3PXD2A-AS1, LINP1) may serve as independent prognostic biomarkers for pancreatic cancer." (PMID 35330729, 2022). "Wound healing assay, transwell assay and cell proliferation assay were performed in order to investigate the effect of LINP1 and SH3PXD2A-AS1 on invasion, migration, and proliferation of pancreatic cancer cells." (PMID 35330729, 2022).
pancreatic ductal adenocarcinoma (2 papers, 2020 to 2022). An infiltrating adenocarcinoma that arises from the epithelial cells of the pancreas. "LINP1 may be involved in the regulation of cell proliferation, cell adhesion and cell cycle-related biological processes in early stage pancreatic ductal adenocarcinoma." (PMID 35330729, 2022).
cutaneous squamous cell carcinoma (1 paper, 2023). "The expression of LINP1 in cutaneous squamous cell carcinoma (cSCC) tissues and cell lines was assessed." (PMID 36918934, 2023).
esophageal squamous cell carcinoma (1 paper, 2023). Esophageal squamous cell carcinoma (ESCC) is a type of esophageal carcinoma (EC) that can affect any part of the esophagus, but is usually located in the upper or middle third. "LINP1 is highly expressed in esophageal squamous cell carcinoma tissues and cell lines." (PMID 36918934, 2023).
cancer (21 papers, 2016 to 2026). A tumor composed of atypical neoplastic, often pleomorphic cells that invade other tissues. "It has been revealed that chromosome 10's LncRNA LINP1 (LINP1) is up‐regulated in cancer of the breast tissues and contributes to the disease's development." (PMID 41459628, 2026). "Through searching The Cancer Genome Atlas (TCGA) database, we found LINP1 is highly upregulated in most cancers (80%) relative to corresponding normal tissues." (PMID 36918934, 2023). "The results indicated LINP1 localizes mainly in the cytoplasm while apparent smaller portion of LINP1 is indeed in the nucleus, which is quite consistent with the previous reports in other cancers." (PMID 36918934, 2023). "Yet, lncRNA LINP1 is over-expressed in multiple cancers and confers resistance to ionizing radiation and chemotherapeutic drugs." (PMID 33045735, 2020). "A number of cancer-implicated lncRNAs, including FAL1, CCAT2, LINP1 (LncRNA In Non-homologous End Joining Pathway 1), and MALAT1, exert their functions through interaction with proteins." (PMID 32503290, 2020). "LINP1 was initially identified as overexpressed in TNBC when compared with other breast cancer subtypes using RNA-seq data from the Cancer Genome Atlas and the Cancer Cell Line Encyclopedia." (PMID 29254281, 2017). "In addition, LINP1 is also up-regulated in a variety of cancers, significantly affecting cancer-related processes such as cell proliferation, migration, invasion, and apoptosis and participating in disease pathogenesis." (PMID 36918934, 2023). "Dysregulated lincRNA-p21 and LINP1 are shown to influence the radiosensitivity of cancer cells." (PMID 28872613, 2017). "If confirmed, LINP1 could plausibly play a dual role in cancer, with overexpression increasing resistance to genotoxic insults and loss of expression promoting chromosome instability." (PMID 27551547, 2016). "LncRNA LUADT1, ZDHHC8P1, JPX, LINP1 and AGAP2‐AS1 have been reported to participate in the development of cancers." (PMID 34547170, 2021). "In this study, LncRNA in non-homologous end joining pathway 1 (LINP1) was identified to be one of the top ten highest-expressed LncRNAs in cSCC, the second most common cancer in the world." (PMID 36918934, 2023). "LINP1 substitutes for PAXX efficiently by (i) increasing the net concentration of NHEJ factors at the double strand break via Ku and (ii) bridging two Ku heterodimers across the double strand break to promote DNA end-joining in NHEJ in cancer cells." (PMID 33045735, 2020). "Kyoto Encyclopedia of Genes and Genomes (KEGG) analysis revealed that LINP1 co-expressed genes are play a role in the AMPK signaling pathway, adherens junction, proteoglycans in cancer, cell cycle, metabolism of xenobiotics by cytochrome P450, and the Hedgehog signaling pathway." (PMID 32913451, 2020).
tumor (19 papers, 2016 to 2025). "In vivo and in vitro experiments show that knockdown of LINP1 causes tumor cells to arrest in the G2/M phase, inhibits cell proliferation and in vivo xenograft tumor growth and significantly promotes cell apoptosis." (PMID 36918934, 2023). "After 7 days, loss of LINP1 led to marked loss of size of xenografts and evident smaller tumor mass formation at the end of the evaluation compared with control group." (PMID 36918934, 2023). "Similarly, LINP1 knockdown in a xenograft model of TNBC cells attenuated tumor growth and was associated with increased γ-H2AX foci after DNA damage." (PMID 27551547, 2016). "We found that EGOT and LINP1 were highly expressed in exosome-free supernatants derived from tumor cells." (PMID 40925917, 2025). "Collectively, our study showed LINP1 is higher-expressed and acts as an oncogene in cSCC to promote the proliferation, colony formation, migration and invasiveness of tumor cells." (PMID 36918934, 2023). "In this study, LINP1 is identified to be significantly higher-expressed in cSCC tumors compared with normal skin tissues and positively correlated with tumor staging." (PMID 36918934, 2023). "LINP1 is highly expressed in most malignant tumor tissues and cells, promotes tumor progression, inhibits apoptosis, and promotes resistance to chemotherapy and endocrine drugs." (PMID 35692795, 2022). "LncRNA in non-homologous end-joining pathway 1 (LINP1) is an oncogene that suppresses tumor growth and metastasis." (PMID 34425750, 2021). "A total of 774 genes were recognized as co-expressing protein coding genes of LINP1 in PDAC tumor tissues, of which 99 were negatively correlated and 675 were positively correlated." (PMID 32913451, 2020). "Such phenomenon suggests that DNA damage repair may be only one of the functions performed by LINP1 in tumor cells and its critical functions in cells are far from full elucidation." (PMID 36918934, 2023). "There is also a correlation between the levels of LINP1 expression and tumor metastasis and stage." (PMID 34425750, 2021). "However, conclusive demonstration that elevated LINP1 levels in TNBCs are a robust indicator of activity and dependence on NHEJ, as compared with tumor types with low-LINP1 expression, will require expanded studies." (PMID 27551547, 2016). "However, blocking LINP1 radio sensitizes the TNBC tumor for radiotherapy." (PMID 37492478, 2023). "Another important lncRNAs are LINP1, TINCR and LINC000473 whose overexpression is also correlated with advanced tumor stage, LNM, and poor pathological differentiation." (PMID 39912983, 2025). "On the other hand, overexpressing LINP1 and EGOT and silencing BREA2 and LINC01503 significantly reduced the sensitivity of tumor cells to T-DM1 and increased their ability to invade and increase their colony formation capacity." (PMID 40925917, 2025). "Interestingly, our findings indicate that the lncRNAs LINP1 and EGOT are released from tumor cells, whereas BREA2 and LINC01503 primarily originate from the exosomes of immune cells." (PMID 40925917, 2025). "Previous studies suggest that lncRNA in non-homologous end joining pathway 1 (LINP1) plays an oncogenic role in tumors and is significantly correlated with tumor progression and prognosis 7-9." (PMID 32913451, 2020).
metabolic disease (1 paper, 2023). A congenital disorder (due to inherited enzyme abnormality) or acquired (due to failure of a metabolically important organ) disorder resulting from an abnormal metabolic process. "Previous studies have shown that Linp1 is one of the key genes in adipogenesis, while RBP4 is elevated and associated with inflammation in metabolic diseases." (PMID 37022192, 2023).
LINP1 also shares sentences with these, for which no sentence is quoted: lung carcinoma (6 papers); gastric cancer (5); glioma (5); hepatocellular carcinoma (4); lung adenocarcinoma (4); bladder cancer (2); colorectal cancer (2); osteosarcoma (2); Breast Invasive Carcinoma (1); clear cell renal cell carcinoma (1); glioblastoma (1); infection (1); Lung Squamous Cell Carcinoma (1); lymph node metastasis (1); melanoma (1); osteoarthritis (1); ovarian carcinoma (1); prostate adenocarcinoma (1); skin disorder (1); stomach cancer (1).